HNRNPA3P1 (heterogeneous nuclear ribonucleoprotein A3 pseudogene 1)
Synonyms: FBRNP; D10S102; formerly HNRPA3; HNRPA3P1
Gene: Processed pseudogene on chromosome 10 (43,789,249 to 43,790,387, reverse strand). Ensembl gene ENSG00000226790.
Diseases named in the same sentence as HNRNPA3P1 in open-access papers:
HNRNPA3P1 is named in the same sentence as 2 diseases in open-access papers, as found by Europe PMC text mining. Sharing a sentence is not in itself a finding about the gene and the disease. The quoted sentences say what the papers report.
tumor (1 paper, 2022). "The results showed that the expression of ACACB, ATP8B4, C14orf28, CIRBP, and DTWD1 were higher in normal tissues, and the content of CDC6, DSP, HMGB3, HNRNPA3P1, PPP1R14C, and TPX2 were higher in tumor tissues." (PMID 35778922, 2022).
HNRNPA3P1 also shares sentences with these, for which no sentence is quoted: vitiligo (1 paper).